ARF3 (ARF GTPase 3)
Description:
GTP-binding protein that functions as an allosteric activator of the cholera toxin catalytic subunit, an ADP-ribosyltransferase. Involved in protein trafficking; may modulate vesicle budding and uncoating within the Golgi apparatus.
Tractability: Small molecule: a structure with a bound ligand is known. Antibody: its Gene Ontology location is reachable by antibodies, with medium confidence. PROTAC: ubiquitination databases record sites on it.
Gene: Protein-coding gene on chromosome 12 (48,935,723 to 48,957,514, reverse strand). Ensembl gene ENSG00000134287.
Subcellular location: Golgi apparatus; Cytoplasm, perinuclear region
Pathways (Reactome):
Vesicle-mediated transport: COPI-dependent Golgi-to-ER retrograde traffic; COPI-mediated anterograde transport
Metabolism: Synthesis of PIPs at the Golgi membrane
Gene Ontology:
Molecular function: protein binding; GTP binding; GTPase activity
Biological process: retrograde vesicle-mediated transport, Golgi to endoplasmic reticulum; intracellular protein transport
Cellular component: extracellular exosome; Golgi membrane; plasma membrane; Golgi apparatus; perinuclear region of cytoplasm
Genetic constraint (gnomAD): Loss-of-function variants: 4 observed, 18.88 expected, observed/expected ratio (o/e) 0.21, 90% interval 0.1 to 0.49. The upper end of that interval is the gene's LOEUF score, 0.49, which puts it in group 2 of 6, group 1 being the genes least tolerant of losing a copy. Missense variants: 76 observed, 228.73 expected, observed/expected ratio (o/e) 0.33, 90% interval 0.28 to 0.4. Synonymous variants: 68 observed, 88.01 expected, observed/expected ratio (o/e) 0.77, 90% interval 0.63 to 0.94.
Homologues: Orthologues: chimpanzee ARF3 (100% identical), dog ARF3 (100% identical), guinea pig ARF3 (100% identical), macaque ARF3 (100% identical), mouse Arf3 (100% identical), pig ARF3 (100% identical), rabbit ARF3 (100% identical), tropical clawed frog arf3 (100% identical), zebrafish arf3b (100% identical), rat Arf3 (99% identical), zebrafish arf3a (99% identical), Drosophila melanogaster Arf1 (93% identical), and 1 more. Paralogues in human: ARF1 (96% identical), ARF4 (79% identical), ARF5 (79% identical), ARF6 (68% identical), TRIM23 (60% identical), ARL1 (56% identical), ARL4C (49% identical), ARL5B (48% identical), ARL2 (47% identical), ARL3 (47% identical), ARL5A (47% identical), ARL4A (46% identical), and 18 more.
Diseases named in the same sentence as ARF3 in open-access papers:
ARF3 is named in the same sentence as 36 diseases in open-access papers, as found by Europe PMC text mining. Sharing a sentence is not in itself a finding about the gene and the disease. The quoted sentences say what the papers report.
breast carcinoma (4 papers, 2020 to 2023). "In breast cancers, ARF3 upregulation was reported as associated with pro-proliferative functions, while in gastric cancer, similar to our findings in prostate cells, ARF3 suppressed proliferative function and in vivo tumorigenesis." (PMID 36880595, 2023). "Additionally, ARF3 was found to be a candidate gene involved in the progression of pregnancy-associated breast cancer, based on integrated analysis of microarray profile datasets." (PMID 32426352, 2020). "Recently, ARF3 expression was positively correlated with breast cancer clinical stages, being upregulated in 92.8% of malignant cases, relative to benign ones." (PMID 32426352, 2020). "Moreover, ARF3 overexpression promotes breast cancer cell proliferation by regulating the cell-cycle G1/S transition, through inhibition of FOXO1 transcription factor activity." (PMID 32426352, 2020). "Besides its behavior as an oncogene in breast cancer, ARF3 has been found downregulated in gastric cancer." (PMID 32426352, 2020). "Indeed, ARF3 mRNA and protein expression levels are upregulated in human breast cancer cell lines and tissues." (PMID 32426352, 2020). "The ARF3 protein is GTP binding and involved with protein trafficking and vesicle binding, the Arf3 has also been suggested as a marker in radiation transformed breast cancer." (PMID 33382739, 2020).
microcephaly (4 papers, 2022 to 2025). A congenital or acquired developmental disorder in which the circumference of the head is smaller than normal for the person's age and sex. "Variants in ARF3 have been associated with generalised developmental delays or ID, frequently presenting with brain and bone irregularities such as microcephaly." (PMID 40689678, 2025). "Interestingly, ARF3 mutations have recently been found in patients with neurodevelopmental disorders characterized by brain abnormalities, microcephaly, and seizures." (PMID 38072052, 2024). "On the other hand, our live imaging of the developing fish forebrain determined the occurrence of altered spindle morphology in microcephaly-causing ARF3 mutants, which might ultimately underlie mitotic arrest and cell death." (PMID 36369169, 2022). "Furthermore, fragmented Golgi has also been recently associated with a neurodevelopmental condition showing microcephaly and caused by mutations in the new disease-gene ARF3, encoding a small GTPase involved in post-Golgi trafficking." (PMID 36034498, 2022). "Of note, our experiments with fluorescently labeled Tfn in combination with staining for EE, RE, and lysosomes unravel a cargo accumulation and delayed recycling in cells expressing ARF3 mutants specifically leading to early-onset microcephaly and severe skeletal defects." (PMID 36369169, 2022).
gastric cancer (3 papers, 2020 to 2023). A primary or metastatic malignant neoplasm involving the stomach. "ARF3, a homolog of ARL14, is said to express itself insufficiently in gastric cancer and may function as a possible biomarker for the prognosis of gastric cancer." (PMID 36874133, 2023). "In fact, ARF3 expression is significantly decreased in gastric cancer stages I-III, when compared with paired normal gastric mucosa tissues, indicating that this protein could be a marker for gastric cancers without metastasis." (PMID 32426352, 2020).
prostate carcinoma (2 papers, 2023). A carcinoma that arises from epithelial cells of the prostate gland. "In contrast, low levels of ARF3/N-cadherin were associated with invasion led by chain-type invasive modality, distal metastasis in xenograft models, and increased lymph-node metastasis in prostate cancer patients." (PMID 37622523, 2023). "This clinical data is consistent with our in vitro data identifying a co-operation between N-cadherin and ARF3, wherein ARF3 and N-cadherin mutually control each other’s levels and function in tumorigenesis, with reduced N-cadherin protein associated with metastatic, recurrent prostate cancer." (PMID 36880595, 2023). "This ARF3/N-cadherin interaction regulates metastasis in vivo and can identify prostate cancer patients with metastatic, poor-outcome disease." (PMID 36880595, 2023). "ARF3 therefore acts as a rheostat for the modality of invasion, which regulates metastasis in vivo and can be used to identify prostate cancer patients with metastatic, poor-outcome disease." (PMID 36880595, 2023). "In vivo, ARF3 levels acted as a rheostat for metastasis from intraprostatic tumor transplants and ARF3/N-cadherin expression can be used to identify prostate cancer patients with metastatic, poor-outcome disease." (PMID 36880595, 2023). "Analysis of progression-free survival of prostate cancer patients (TCGA) indicated that neither ARF3 nor CDH2 mRNA levels could stratify patient groups with altered survival." (PMID 36880595, 2023). "Indeed PSD/EFA6 shows robust activation of the Class I ARF, ARF1, when membranes are included in in vitro assays, and a preference for the Class I ARF GTPase ARF3, and not ARF6, in invasive prostate cancer cell lysates." (PMID 37622523, 2023).
anemia (1 paper, 2024). A reduction in the number of red blood cells, the amount of hemoglobin, and/or the volume of packed red blood cells. "A second cluster involved multiple markers of anemia (transferrin and serum iron), strongly associated with markers of one-carbon metabolism (B12, folate), liver metabolism (GGT, ALT, AST, LDH), ADP-ribosylation factors 1 and 3 (ARF1, ARF3), and the structural protein desmatin (DMTN)." (PMID 38543504, 2024).
metastatic disease (1 paper, 2023). "We examined whether levels of ARF3 and/or N-cadherin may identify patients with poor outcome or metastatic disease." (PMID 36880595, 2023).
poliovirus infection (1 paper, 2014). An disease or disorder caused by infection with Enterovirus C. "Arf1, Arf3, and Arf5 were reported to be activated upon poliovirus infection." (PMID 24911624, 2014).
renal fibrosis (1 paper, 2024). A final common manifestation of a wide variety of chronic kidney diseases characterized by glomerulosclerosis and tubulointerstitial fibrosis. "Functionally, ectopic overexpression of circ_Arf3 in MCs reversed HG-induced proliferative activity, moreover, circ_Arf3 up-regulation reduced the accumulation of ECM-related proteins including α-SMA, FN, Col I, and Col IV in cells, thus preventing renal fibrosis." (PMID 39120858, 2024). "Besides that, the results of western blotting also showed that the expression levels of the well-known renal fibrosis-related factors, α-SMA, FN, Col I, and Col IV were decreased by circ_Arf3 overexpression in MCs under HG condition." (PMID 39120858, 2024).
sarcoma (1 paper, 2021). A usually aggressive malignant neoplasm of the soft tissue or bone. "Among them, high expression levels of SMARCC1, SRSF10, PRPF38A, JARID2, GNAI3, miR-301a-3p, miR-106b-5p, miRNA-130b-3p, miR-423-3p and LINC01296 and low expression levels of ARF3 and PRKCB were associated with shorter overall survival in sarcomas." (PMID 33653335, 2021). "However, the high expressions of ARF3 and PRKCB were significantly associated with longer overall survival (P = 0.0018 and P = 0.0162), indicating that ARF3 and PRKCB overexpression could be positive prognostic factors in sarcoma patients." (PMID 33653335, 2021).
Sepsis (1 paper, 2020). Sepsis is defined as life-threatening organ dysfunction caused by a dysregulated host response to infection. "In conclusion, this study showed that BIG1 plays a crucial role in mediating the activation of TLR4-MyD88 signaling pathways through its interaction with ARF3 during the pathological process of sepsis." (PMID 32415087, 2020).
infection (6 papers, 2012 to 2025). The state of being infected such as from the introduction of a foreign agent such as serum, vaccine, antigenic substance or organism. "and Arf3-, Arf4-, and Arf5-depleted cells, indicating normal progression of the immediate–early and early phases of infection in these cells." (PMID 34440611, 2021). "The endogenous expression level and membrane recruitment of Arf1 and Arf3 was relatively low in Balb 3T3 cells immediately after infection (0 hpi), which was similar to the uninfected cells." (PMID 34440611, 2021). "A similar pattern was observed for Arf3 in the early phase of infection." (PMID 34440611, 2021). "However, TGN-derived elements, at least those controlled by ARF3 and Rab6, appear to continue to change in the L phase of infection, after expression of L-phase genes and viral structural proteins." (PMID 33042998, 2020). "Since ARNO has been shown to activate Arf3 and Arf6 in vitro, we examined whether any additional Arf GTPases promote invasion by depleting Arf3, Arf4, Arf5, and Arf6 individually by siRNA transfection of HeLa cells 72 hr before infection with WT Salmonella." (PMID 22341462, 2012). "In conclusion, our study demonstrates a significant role of Arf1, Arf3, Arf4, and Arf6 in the pathogenesis of CMV infection and host cell reorganization during the early phase of infection." (PMID 34440611, 2021). "The specificity of the interactions between ARF5 and the three WRKYs was confirmed by co-expressing ARF3 (AT2G33860)-cYFP, which naturally lacks domain III and IV, and WRKY53-cYFP, expressed early after infection with A. tumefaciens strain C58 (3 hpi)." (PMID 25615824, 2015).
neurodevelopmental disorder (3 papers, 2022 to 2024). A behavioral and cognitive disorder with onset during the developmental period that involves impaired or aberrant development of intellectual, motor, or social functions. "Here we identify de novo missense ARF3 variants as the molecular event underlying a clinically variable neurodevelopmental disorder characterized by DD/ID and variable CNS defects as common features." (PMID 36369169, 2022). "In conclusion, our work identifies ARF3 as a gene implicated, when mutated, in a clinically variable neurodevelopmental disorder belonging to the emerging class of “Golgipathies”12,13." (PMID 36369169, 2022). "The finding of fragmented Golgi in cells and embryos expressing the disease-associated ARF3 mutants assigns this disorder to the recently defined family of “Golgipathies”, a group of heterogeneous neurodevelopmental disorders clinically characterized by a wide spectrum of CNS abnormalities." (PMID 36369169, 2022). "Similar to ARF3, mutations in neuronal AP3 isoforms can lead to neurodevelopmental disorders with some overlapping features with other synaptopathies, suggesting a potential functional overlap of Mint1 and AP3 in synaptic integrity." (PMID 38072052, 2024).
cancer (2 papers, 2022 to 2024). A tumor composed of atypical neoplastic, often pleomorphic cells that invade other tissues. "Focusing on the nervous system disorders, ARF3 presented a higher association score, and it was related to more diseases than IPO7, which was more related to measurement, cancer, and gastrointestinal diseases." (PMID 35742897, 2022). "ARFs family (ARF1, ARF3, ARF4, ARF5, ARF6) are generally highly expressed in Pan-cancer." (PMID 38617932, 2024). "The cancer promoting effects of ARF1, ARF3, ARF4 and ARF6 in individual cancers have been studied, only the role of ARF5 in cancer has not been reported." (PMID 38617932, 2024).
tumor (1 paper, 2023). "Collectively, this suggests that rather than controlling set levels of high or low N-cadherin (from overexpression or KD, respectively) ARF3 overexpression effects an even distribution of N-cadherin expression across tumor cells." (PMID 36880595, 2023). "Indeed, in our own analysis while ARF3 expression was commonly altered in tumor compared to normal tissue, the directionality of expression change was dependent on tumor type." (PMID 36880595, 2023). "Similarly, high levels of CDH2 protein and ARF3 mRNA identified a patient group with lowest levels of new tumor formation after initial therapy, while all other groups showed similar rates." (PMID 36880595, 2023). "This revealed that while ARF3 mRNA levels are widely altered in tumor versus normal tissue, the directionality of ARF3 mRNA alternation in tumors is dependent on tissue type and that ARF3 mRNA expression is not a consistent indicator of clinical characteristics." (PMID 36880595, 2023).
ARF3 also shares sentences with these, for which no sentence is quoted: Atrophy (1 paper); candidiasis (1); Costello syndrome (1); developmental delays (1); diabetic nephropathy (1); epilepsy (1); esophageal carcinoma (1); ganglioglioma (1); gastrointestinal disease (1); glioblastoma multiforme (1); Huntington disease (1); Intellectual disability (1); Lissencephaly (1); nervous system disorder (1); Obesity (1); Periventricular heterotopia (1); postherpetic neuralgia (1); prostate adenocarcinoma (1); Seizure (1); skin cutaneous melanoma (1); speech delay (1); thymoma (1).